FAF1 (Fas associated factor 1)
Diseases named in the same sentence as FAF1 in open-access papers (continued):
Sharing a sentence is not in itself a finding about the gene and the disease.
cancer (continued). "On the other hand, we found that FAF1 mRNA expression was higher in well-differentiated cancer tissue than in poorly differentiated cancer tissue." (PMID 23304123, 2012). "Our study supports an augmented model in which animal miRNAs can regulate mRNAs by binding to targets outside as well as inside the 3′ untranslated region, and extends our understanding of how miR-24 and FAF1 regulate apoptosis in cancer cells." (PMID 20195546, 2010). "Previous research found that functional loss, rather than the overexpression of FAF1, was frequently found in cancers of various origins." (PMID 37999107, 2023). "FAF1 is still a candidate target for anti-cancer therapy development." (PMID 37999107, 2023). "FAF1 has been found to play an important role in normal neuronal cell survival and proliferation, whereas FAF1 downregulation may play a role in cancer through a variety of mechanisms." (PMID 38031027, 2023). "Aberrant FAF1 is linked to the development of various cancers according to previous reports, but the link is not clear." (PMID 37999107, 2023). "Furthermore, FAF1 was present in the CM of each of a number of various cancer cell types (MCF-7, HeLa, PANC-1, and MIA PaCa-2 cells)." (PMID 32831099, 2020). "Moreover, FAF1 expression is downregulated in various cancers, including lung, colon, liver, prostate, brain, ovarian, and breast cancers." (PMID 32831099, 2020). "A loss of FAF1 function could cause constitutive WNT pathway activity (consistent with the downstream inductions of IGF2BP1 and E2F1 in this cancer)." (PMID 25861239, 2015). "We found that miR-24 regulates apoptosis by targeting FAF1 in cancer cells." (PMID 20195546, 2010). "IGF2BP1 may be upregulated as a consequence of mutated FAF1 not being able to suppress WNT signaling in this specific cancer." (PMID 25861239, 2015). "For example, most cancer tissues exhibit weak to moderate cytoplasmic and/or nuclear immunoreactivity in the ASPSCR1, UBXN2A, UBXN10, UBXN1, FAF1, FAF2, UBXD2B proteins." (PMID 38365777, 2024). "Other reported targets of miR-24 include proapoptotic (FAF-1, Caspase-9, Bim, and Apaf-1) and cell cycle proteins; miR-24 was also shown to regulate XIAP, reducing the threshold for apoptosis in cancer cells." (PMID 28061479, 2017). "Future studies will enable illustration of the therapeutic potential of FAF1 in various types of cancer and help improve understanding of the anti-cancer mechanism of the UBXD family in human cancers." (PMID 27754413, 2016). "FAF-1-dependent degradation of HSP70 reduces colony formation and induces apoptosis in cancer cells." (PMID 27754413, 2016). "Furthermore, FAF1 destabilizes TβRII on the cell surface by recruiting VCP/E3 ligase complex, thereby suppressing TGF-β-mediated cancer metastasis." (PMID 38172660, 2024). "While ubiquitin-like domains are critical for the anti-cancer roles of FAF1, the presence of non-related ubiquitin domains further promotes the anti-cancer role of FAF1." (PMID 27754413, 2016). "Notably, analysis of the cancer datasets via cBioPortal database revealed that the mRNA level of SAP130 was negative correlated with FAF1 mRNA level in several types of cancers." (PMID 38172660, 2024). "According to our review, no studies have investigated the cancer stemness of FAF1." (PMID 38365777, 2024). "On the other hand, FAF1’s interaction with polyubiquitinated proteins, the p97 complex, heat shock protein 70 (HSP70), and the members of the Fas-signaling pathway enable this UBX domain-containing protein to play a critical role in the pathogenesis of human cancers." (PMID 27754413, 2016).
infection (6 papers, 2017 to 2024). The state of being infected such as from the introduction of a foreign agent such as serum, vaccine, antigenic substance or organism. "We show that a nonsense variant in a predicted paralogue of FAS-associated factor 1 (FAF1) in this region is also associated with survival in an independent cohort, and is linked to rates of cell expansion during infection." (PMID 35446841, 2022). "Further evidence for this idea comes from the association between FAF1 expression and infection with Helicobacter pylori, a Group I carcinogen in gastric carcinogenesis." (PMID 28030825, 2017). "FAF1gt/gt mice were more susceptible to infection with VSV than FAF1+/+ mice, resulting high mortality in FAF1gt/gt mice due to a high viral load in the organs." (PMID 28542569, 2017). "Furthermore, we examined the expression of mRNA encoding IFN-related genes in BMDMs and PBMCs isolated from FAF1+/+ mice and FAF1gt/gt mice after infection with PR8-GFP or VSV-GFP." (PMID 28542569, 2017). "For instance, a study investigating the regulatory role of FAS-associated factor 1 (FAF1) on ROS production showed that RAW cells produced significantly less IL-6 and IL-12 but more NO compared to BMDM after infection with Listeria monocytogenes (L.m)." (PMID 39445217, 2024). "Collectively, these results suggest that FAF1 in macrophages effectively augments p67phox stability in response to infection with L. monocytogenes, resulting in increased phagocytosis-mediated NADPH oxidase activity." (PMID 31412082, 2019). "Upon infection by L. monocytogenes, FAF1 interacts with p67phox (an activator of the NADPH oxidase complex), thereby facilitating its stabilization and increasing the activity of NADPH oxidase." (PMID 31412082, 2019). "Here, we show that the apoptotic protein FAF1 regulates ROS production in macrophages by regulating phagocytic NADPH oxidase activity upon infection by L. monocytogenes." (PMID 31412082, 2019). "Taken together, these findings demonstrate that FAF1 enhances inflammatory responses and intracellular bacterial clearance via ROS generation by interacting with p67phox upon infection by L. monocytogenes." (PMID 31412082, 2019). "Taken together, these data suggest that FAF1 positively regulates type I IFN signaling in response to infection by RNA viruses." (PMID 28542569, 2017). "Together with this, significantly decreased type I IFN, ISGs, and antiviral mRNA transcript levels were observed in BMDMs and PBMCs of FAF1gt/gt mice compared with those in FAF1+/+ mice after infection with VSV and PR8." (PMID 28542569, 2017). "Importantly, mRNA expression of FAF1 was induced with 2–3 folds at 15 or 60 m post-infection (mpi) with L. monocytogenes in Raw264.7 cells, suggesting that FAF1 responds to bacterial infection at early time." (PMID 31412082, 2019). "Based on a previous study of the role of FAF1 in antiviral responses against infection by RNA virus, we asked whether FAF1 is also involved in responses to bacterial infection." (PMID 31412082, 2019). "Hence, the present data indicate that FAF1 targets NLRX1 to regulate type I IFN production upon infection with RNA virus only." (PMID 28542569, 2017). "Similar results were obtained from BMDMs of FAF1+/+ mice after infection of PR8-GFP or VSV-GFP." (PMID 28542569, 2017). "FAF1 interacts directly with p67phox and stabilizes p67phox, thereby triggering NADPH oxidase-mediated ROS production, release of proinflammatory cytokines, and bacterial clearance in response to infection by L. monocytogenes." (PMID 31412082, 2019). "Consequently, knockdown or ectopic expression of FAF1 had a marked effect on production of ROS, proinflammatory cytokines, and antibacterial activity, in macrophages upon stimulation of TLR2 or after infection with L. monocytogenes." (PMID 31412082, 2019). "In addition, we examined phosphorylation of target proteins in FAF1 knockdown and FAF1-reconstituted MEFs after PR8-GFP infection." (PMID 28542569, 2017).
infection (continued). "Comparison of HGC-27/FAF1 infected or not infected with H. pylori showed that infection slightly reduced expression of FAF1 but increased expression of NF-κB, based on iTRAQ and Western blotting of total cell lysates." (PMID 28030825, 2017).
adenocarcinoma (2 papers, 2012 to 2023). A common cancer characterized by the presence of malignant glandular cells. "FAF1 expression was significantly higher in advanced pathological stage adenocarcinoma (p = 0.002), worse regional lymph node metastasis (p = 0.014), and positive EGFR mutation (p = 0.006)." (PMID 37999107, 2023). "In this study, we discovered that FAF1 was significantly higher in tumoral tissues compared to non-tumoral tissues in NSCLC, and that it was significantly associated with poor prognosis, particularly in adenocarcinoma." (PMID 37999107, 2023).
bacterial infection (1 paper, 2019). "This study reveals that FAF1 is a crucial regulator that induces inflammatory responses to bacterial infection via ROS production." (PMID 31412082, 2019). "Also, FAF1 responded to high MOI of bacterial infection in mouse bone marrow-derived macrophages (BMDMs) and Raw264.7 cells." (PMID 31412082, 2019). "Interestingly, FAF1gt/gt mice deficient in FAF1 expression exhibit weakened inflammatory responses and are thus more vulnerable to bacterial infection than FAF1+/+ mice." (PMID 31412082, 2019). "To better understand the biological role of FAF1, we examined the relationship between NADPH oxidase and FAF1 in host defense against bacterial infection." (PMID 31412082, 2019). "However, the role of FAF1 in defense against bacterial infection remains unclear." (PMID 31412082, 2019). "However, the role of FAF1 in host defense against bacterial infection remains unclear." (PMID 31412082, 2019).
FAF1 also shares sentences with these, for which no sentence is quoted: amyotrophic lateral sclerosis (2 papers); malignant mesothelioma (2); mesothelioma (2); amyloidosis (1); autism (1); breast tumors (1); Brugada syndrome (1); cleft palate (1); colorectal adenocarcinoma (1); Cornelia de Lange syndrome (1); diffuse large B-cell lymphoma (1); haemorrhage (1); hearing loss (1); Helicobacter infection (1); intervertebral disc degeneration (1); Joubert syndrome 31 (1); lung large cell carcinoma (1); metabolic disorders (1); metastasis (1); neurodegenerative disease (1); pancreatic cancer (1); prostate adenocarcinoma (1); retinal degeneration (1); sarcoma (1); short-rib thoracic dysplasia (1); systemic lupus erythematosus (1); Theileria infection (1); thyroid carcinoma (1); tooth agenesis (1); toxoplasmosis (1).
A further 1 disease shares a sentence with FAF1 in 1 paper.